CRP (C-reactive protein)
Diseases named in the same sentence as CRP in open-access papers (continued):
Sharing a sentence is not in itself a finding about the gene and the disease.
anemia (continued). "Laboratory investigations, including erythrocyte sedimentation rate (ESR), C-reactive protein (CRP), full blood count, renal and liver function, glucose, electrolytes, and thyroid profile, were all within normal limits except for mild anemia and borderline hyponatremia." (PMID 40438877, 2025). "Laboratory results may reveal increased erythrocyte sedimentation rate, anemia, and elevated C-reactive protein (CRP) levels." (PMID 40705140, 2025). "Laboratory findings demonstrated anaemia, mild neutrophilia and a raised C-reactive protein (CRP)." (PMID 40416187, 2025). "CBC and biochemistry results included microcytic hypochromic mildly regenerative anaemia, thrombocytosis, hypoalbuminaemia and hyperglobulinaemia with decreased A/G ratio, increased serum concentration of CRP, severe hyperfibrinogenaemia, and increased ALKP activity." (PMID 39814065, 2025). "At an age of 15, she was then admitted with acute severe colitis, presenting with a Pediatric Ulcerative Colitis Activity Index (PUCAI) score of 80, anemia, C-reactive protein (CRP) 92.5 mg/L, calprotectin 1390 mg/kg, low-grade fever, and significantly reduced condition." (PMID 41007133, 2025). "Systemic inflammatory markers, including anemia (49% of cases), elevated gamma globulins (45%), increased erythrocyte sedimentation rate (55%), and elevated C-reactive protein (75%), have been reported, suggesting an inflammatory response secondary to tumor presence." (PMID 40264618, 2025). "Laboratory findings included mild microcytic hypochromic non‐regenerative anaemia, marked hyperglobulinaemia, decreased A/G ratio, increased serum concentration of CRP, severe hyperfibrinogenaemia, and increase in ALKP, alanine aminotransferase (ALT) and aspartate aminotransferase (AST) activities." (PMID 39814065, 2025). "Screening for deficiencies of iron, B12, and folate was generally low, with limited testing for serum ferritin (33.7%), TSAT and serum iron (11.2% each), and vitamin B12 and folate levels (19.8% and 17.6%, respectively) with CRP measurements available for 21.0% of patients with anaemia." (PMID 38092441, 2024). "Moreover, prolonged IL-6 activation induces anemia and elevates plasma levels of CRP and immunoglobulins, potentially affecting the intestinal microbiota." (PMID 39703501, 2024). "Anemia (39%), high urea (52%), hyperbilirubinemia (18%), increased alkaline phosphatase (16%), increased CRP (C‐reactive protein; 27%), and increased troponin (98.2%) were common findings in the overall population, whereas hyponatremia (6%) and hypoalbuminemia (2%) were less common." (PMID 38314569, 2024). "On admission, laboratory analysis revealed anemia, renal dysfunction (eGFR 30 mL/min/1.73 m2), polyclonal gammopathy (IgG 7130 mg/dL), elevated serum IgG4 level (2130 mg/dL), and increased C-reactive protein (8.0 mg/dL)." (PMID 38472948, 2024). "In this case, we can only look for clues of “incomplete Kawasaki disease” from follow-up laboratory tests, such as increased C-reactive protein (CRP), increased erythrocyte sedimentation rate, anemia, increased platelet, hypoalbuminemia, aseptic pyuria, increased alanine aminotransferase, and so on." (PMID 39093792, 2024). "The high ESR and CRP levels reflect persistent inflammation, while anemia and low serum iron levels could be due to chronic disease and underlying infection." (PMID 39445278, 2024). "Notably, the child had severe anaemia (Hb of 5.5 g/dL), an elevated white blood cell count, elevated C-reactive protein and random blood glucose on admission ranged between 9.5 mmol/L and 11.5 mmol/L." (PMID 39040874, 2024). "After induction chemotherapy, before the start of radiochemotherapy the most common grade 1–2 adverse event observed was anemia in 79.6% of patients, followed by an increase in CRP grade 1–2 in 55.3% of patients and increased LDH grade 1–2 in 43.6% of patients." (PMID 38877146, 2024).
anemia (continued). "Additionally, our patient had severe anaemia that required a blood transfusion and an elevated C-reactive protein." (PMID 39040874, 2024). "Non-traditional cardiovascular risk factors such as anaemia, C-reactive protein, or frailty markers were of very low prevalence in our general population sample." (PMID 38337463, 2024). "In our results, we found a significantly increased CRP in patients with anaemia." (PMID 38602554, 2024). "However, in our case, microcytic hypochromic anaemia, along with apparently normal ferritin and a high ESR and CRP, were likely due to a concomitant iron deficient status along with a generalized inflammatory state." (PMID 38933629, 2024). "A recent study of patients with CKD that examined the association between anemia, GDF-15, and hepcidin found significant correlations between hepcidin levels and iron and CRP and significant correlations between serum GDF-15 and Hb levels, ferritin, iron, and CRP." (PMID 38883134, 2024). "Her laboratory tests showed mildly increased CRP (0.45 mg/dL) and mild anemia (11.2 g/dL)." (PMID 39070404, 2024). "Many studies have observed the increase of CRP in patients with TB-related anemia." (PMID 38886797, 2024). "To date, the major risk factors associated with CALs have been reported to be as follows: male gender, Asian ethnicity, age younger than 12 months, incomplete clinical form, late treatment, longer fever duration, IVIG resistance, elevated CRP, anemia and hypoalbuminemia." (PMID 39335523, 2024). "ID prevalence increased significantly with the presence of more than three comorbidities (65.6% vs. 55.9%; p = 0.0274), CRP ≥ 12 mg/L (73.0% vs. 49.3%; p < 0.001) and treatment that may influence ID/anemia (60.5% vs. 49.6%; p = 0.0042)." (PMID 38287253, 2024). "The most frequent analytical finding is peripheral eosinophilia, but hypergammaglobulinemia, anemia, elevated C-reactive protein, sedimentation rate, and elevated transaminases may also occur." (PMID 39726513, 2024). "In the risk model, six inflammation-related parameters i.e., the presence of anemia, elevated counts of neutrophils and platelets and elevated levels of CRP, ESR and LDH, were each awarded one point and combined, i.e., a score of 0–6 risk points for each patient." (PMID 38049762, 2023). "However, 3 months after starting treatment, anemia had further deteriorated, and her inflammatory markers remained elevated (Hb 67 g/L; CRP 34 mg/L; SAA 47.4 mg/L; ESR 77)." (PMID 37744344, 2023). "An increase in C-reactive protein concentration and anemia were observed in all patients." (PMID 37676863, 2023). "Moreover, severe anaemia, thrombocytopenia, and high CRP levels occurred more frequently in children with malaria." (PMID 37087435, 2023). "Our results confirmed the increased mortality risk with the elevation of the inflammatory (C-reactive protein, serum ferritin, and LDH) and coagulation biomarkers (INR and D-dimer), anaemia, thrombocytopenia, leucocytosis, impaired hepatic and renal functions, and disturbance of electrolytes levels." (PMID 36750802, 2023). "Fuhrman grade of 3 or 4, anaemia, C-reactive protein (CRP) of > 3 mg/L, Charlson Comorbidity Index (CCI) ≥ 3, and advanced tumor T-stage (T3/T4) were also all significant negative predictors of OS; whereas, only Fuhrman grade 3–4 and advanced tumor T-stage were also negative predictors of RFS." (PMID 37875832, 2023). "However, 14.5% (n=16), 59.1% (n=65), 0.1% (n=1) and 89.1% (n=98) of patients had leukopenia, anaemia, thrombocytopenia and raised C-reactive protein, respectively." (PMID 37415953, 2023). "Deranged hematological and biochemical laboratory findings in the form of anemia, neutrophilia, lymphopenia, raised postprandial blood sugar (PPBS), HbA1c, serum creatinine, c-reactive protein (CRP), pro-calcitonin, D-Dimer, and IL-6 has been associated with COVID-19 disease." (PMID 37284389, 2023). "There was a decrease in the CRP level, mild anemia, and an increase in the platelet number." (PMID 38138107, 2023).
anemia (continued). "Additionally, other possible biomarkers including anemia, C-reactive protein, and cystatin C have been identified." (PMID 37096248, 2023). "The impact of the hematocrit (Hct) on CRP values: usually POC CRP assays do not adjust for hematocrit, due to this limitation there is the risk of overestimate CRP concentrations when Hct is elevated or underestimate CRP concentrations among patients with anemia due to chronic disease." (PMID 36662693, 2023). "Six inflammation-related parameters i.e., elevated values of neutrophils, platelets, C-reactive protein (CRP), erythrocyte sedimentation rate (ESR) and lactate dehydrogenase (LDH), and the presence of anemia, were each scored with one point, giving 0–6 risk points for each patient." (PMID 38049762, 2023). "Similarly, several clinical factors were associated with higher 10-year mortality like having the procedure performed in western Europe and North American, current smoking, COPD, elevated CRP, anemia, and an increased HbA1c." (PMID 37396431, 2023). "Combined anemia is defined by ferritin serum level < 100 μg/L and high levels of CRP." (PMID 37686856, 2023). "Patients were screened for anemia (< 12.0 g/dL in women and < 13.0 g/dL in men) and ID (either absolute [ferritin < 30 μg/L] or functional [ferritin ≥ 30 μg/L + transferrin saturation < 20% + C-reactive protein > 5 mg/L])." (PMID 37434251, 2023). "High serum CRP and ferritin levels point to a fat liver with iron deposits and anemia." (PMID 37760862, 2023). "Predictors of VTE after MPMs were female gender, history of VTE prior to MPMs diagnosis, metastatic first primary malignancy, poor performance status, anemia, elevated CRP level at MPMs diagnosis, ICU admission after MPMs diagnosis, chemotherapy, and referral to palliative care." (PMID 36314077, 2023). "Laboratory abnormalities are often unspecific but may include elevation in erythrocyte sedimentation rate, C-reactive protein and globulin levels and anemia." (PMID 37892598, 2023). "In these situations, other clinical tests, such as the serum iron, transferrin saturation, soluble transferrin receptor (sTfR), sTfR /log ferritin or C-reactive protein, may be useful adjunctive tests to assist in the diagnosis anemia." (PMID 36823529, 2023). "Laboratory findings may reveal an increase in white cell count, anemia, elevated CRP, elevated creatinine, hypoalbuminemia, and hyperglycemia." (PMID 40729205, 2023). "The patient had elevated CRP, anemia, hypoalbuminemia and hyponatremia." (PMID 37848930, 2023). "This study involved an analysis of 150 children who were evaluated based on their duration of presentation with seizures from the onset of fever, family history of FS and seizure disorder, anemia levels, temperature at presentation, C-reactive protein (CRP) test results, and sodium levels." (PMID 38187992, 2023). "Elevated preoperative levels of fibrinogen, cystatin-C, C-reactive protein (CRP), and neutrophil-to-lymphocyte ratio (NLR) (> 2.7) are associated with LN involvement, as well as low albumin-globulin ratio (AGR) (< 1.45), and preoperative anemia." (PMID 37801187, 2023). "This can be reflected by anemia, low albumin, and elevated CRP." (PMID 37878974, 2023). "Inflammatory parameters (e.g., ESR, CRP, fibrinogen, anemia) could be lower in GCA patients with stroke, although mean ESR remains similar in others." (PMID 38130834, 2023). "From our results, the high ferritin levels associated with CRP and GDF-15 may indicate the link between iron homeostasis and the inflammatory response through anemia of inflammation or chronic disease." (PMID 37649102, 2023). "On the other hand, elevated CRP concentration was only associated with an increased risk of anemia in males but not females, demonstrating that NLR performed better than CRP as an early predicator of anemia, particularly in females." (PMID 37763711, 2023). "Patients typically presented with anemia and an elevated C-reactive protein count." (PMID 35451395, 2022).
anemia (continued). "We observed significant positive correlations of the total PR3 blood pool with clinical markers of systemic inflammation, such as CRP; anemia, such as hemoglobin; and kidney injury, such as creatinine and erythrocyturia, in patients with PR3-AAV but not in patients with MPO-AAV." (PMID 36125911, 2022). "Among HIV-infected low BMI (-5.4 kj/kg/day, 95%CI: -10.4, -0.4), moderate anaemia (-13.8 kj/kg/day, 95%CI: -18.8, -8.8), CD4 counts ≤200cells/uL (-9.9 kj/kg/day, 95%CI: -16.5, -3.3) and log CRP (-9.7 kj/kg/day, 95%CI: -12.4,-7.0) were associated with lower PAEE." (PMID 35061774, 2022). "The laboratory tests performed pointed out lymphopenia, thrombocytopenia, anemia, elevated C-reactive protein – CRP, erythrocyte sedimentation rate and ferritin levels, hyponatremia, hypopotassemia, hypertriglyceridemia, elevated D-dimer, in-creased troponin and NT-proBNP." (PMID 36474612, 2022). "In adult cohorts with chronic kidney disease, scholars have found that CRP exacerbated anemia by inhibiting endogenous/exogenous erythropoietin, which may contribute to a synergic effect between inflammation and anemia on unfavorable events." (PMID 36405830, 2022). "Other lab findings may also be present but are non-specific such as changes in erythrocyte sedimentation rate (ESR), CRP, and normocytic normochromic anemia." (PMID 36569738, 2022). "Tumor markers (CEA and CA 19.9), anemia markers (hemoglobin, hematocrit and medium corpuscular volume) and inflammatory markers (leukocytes, neutrophils, N/L index, platelets, fibrinogen, C-reactive protein, CRP and IL-6) were also determined." (PMID 36232966, 2022). "In multivariate analysis, the RDW was independently associated with five-year mortality (hazard ratio, HR = 1.12; 95% CI 1.01 to 1.24; p = 0.01) after adjusting for age, cardiovascular disease, FEV1, PaCO2, anaemia, C-reactive protein, pulmonary hypertension, and right ventricular dysfunction." (PMID 36233510, 2022). "Interestingly, several factors identified in our study, including anemia, lymphopenia, thrombocytosis, and a high CRP level, reflect inflammatory markers." (PMID 36233666, 2022). "We next assessed whether inflammation marker C-reactive protein (CRP) and neutrophils counts, and anemia marker hemoglobin content (Hb) were correlated with serum CXCL13 levels in the IBD patients." (PMID 36172372, 2022). "While hepcidin and CRP examination may point to the pathogenesis of anaemia, we discovered that hepcidin and IL-6 examination may predict the development of anaemia during hospitalization in female lung cancer patients." (PMID 36612220, 2022). "Patients with TB of the hip joint had anemia and increased serum CRP levels prior to treatment." (PMID 36578841, 2022). "C-reactive protein (CRP) and ferritin are elevated in TB patients with anemia." (PMID 36106202, 2022). "Frailty was also associated with a low-grade chronic pro-inflammatory state characterised by increased levels of CRP and IL-6, and could further result in anaemia." (PMID 35172806, 2022). "These may include anemia, hyperlipidemia (30–50% of patients), and elevation of the erythrocyte sedimentation rate and C-reactive protein (50% of cases)." (PMID 36362761, 2022). "Laboratory examination revealed elevated ESR and CRP and anemia." (PMID 36494678, 2022). "Our results demonstrate that PMF patients, harboring a homozygous JAK2V617F genotype, display the higher plasma EDA-FN concentrations and that elevated blood EDA-FN significantly correlates with anemia, high levels of hs-CRP, grade of BM fibrosis and splanchnic vein thrombosis at diagnosis." (PMID 36212480, 2022). "Enterocolitis may result in anaemia, elevated C-reactive protein (CRP), and decreased serum albumin." (PMID 36139530, 2022).
anemia (continued). "Many altered biochemical parameters such as anaemia, thrombocytopenia, elevated bilirubin, CRP, procalcitonin, AST, ALT, ferritin, GGT, IL 6, and reduced sodium and albumin levels can be related to both malaria and MIS-C therefore require proper interpretation." (PMID 35897103, 2022). "Hence, increased hepcidin concentrations in combination with high CRP concentrations enable us to determine the presence of inflammation in the pathogenesis of anaemia in lung cancer males admitted to the hospital with anaemia." (PMID 36612220, 2022). "Weight change, anemia, hypoalbuminemia, and CRP were longitudinally analyzed." (PMID 35331196, 2022). "Determining aetiologic indicators of anaemia like iron status (ferritin), inflammatory markers and C‐reactive protein (CRP), malaria status, genetic blood disorders and haemoglobinopathies in population‐based survey would be important to implement context‐specific interventions." (PMID 32761751, 2021). "Anemia, hypoalbuminemia, and elevated CRP levels were noted in patients with CMV enteritis." (PMID 34407879, 2021). "In addition, systemic inflammatory response (SIR) parameters like the C-reactive protein (CRP), the neutrophil–lymphocyte ratio (NLR), anemia and others have been correlated with the risk of recurrence and overall survival in curative treated malignancies." (PMID 34055606, 2021). "Patients with a high CONUT grade had a lower BMI, higher EuroSCORE II, greater incidence of cerebrovascular accident, myocardial infarction within within 1 month, and anaemia, lower creatinine/CysC ratio, and higher C-reactive protein levels than those with a low CONUT grade did." (PMID 34413410, 2021). "In addition, lymphopenia, thrombocytopenia, anemia, elevated levels of creatinine, transaminases and C-reactive protein are often encountered." (PMID 34185152, 2021). "By this stage, serum PSA level, bone destruction and osteoblastic activity, anemia, and inflammatory response (CRP), and an increased incidence of organ metastasis could synergically affect general deterioration." (PMID 34148264, 2021). "Among 30 variables considered at onset, nine (age at onset, fever, weight loss, symmetry, focality, functional limitation, anemia, elevated ESR, CRP) resulted statistically significant in differentiating the three clinical entities from each other and were chosen to build up a decisional tree." (PMID 33830308, 2021). "In addition, Hgb was negatively correlated with CRP, suggesting a possible role of inflammatory conditions or diseases in anemia genesis." (PMID 33801005, 2021). "Here, we identified anemia, CRP, NLR, LMR and ECOG as prognostic factors for overall survival." (PMID 34055606, 2021). "Measures could be taken to keep an ideal CRP level to avoid the electrolyte imbalance and anemia of chronic disease, while effective anti-CRP intervention may benefit the prevention of hypercholesterolemia and neurological diseases." (PMID 34386016, 2021). "Now that CRP is highly sensitive to bacterial infection and is not affected by gender, age, anemia, and other factors, CRP has a high diagnostic value for infection-related diseases." (PMID 34589449, 2021). "The severity of COVID‐19 was found significantly associated with anemia, lymphocytopenia, and significant increase of neutrophil‐to‐lymphocyte ratio, ferritin, fibrinogen, aminotransferases, lactate dehydrogenase (LDH), C‐reactive protein (CRP), and D‐dimer." (PMID 33190411, 2021). "Laboratory tests are nonspecific and may reveal elevated inflammatory markers, including erythrocyte sedimentation rate, C-reactive protein, elevated white blood cell count with hypereosinophilia, anemia, and thrombocytopenia." (PMID 34540395, 2021). "Severe anemia, leukocytosis and elevated C-reactive protein were also common (29%–49%)." (PMID 34448744, 2021). "UBA1 should be sequenced in this population, especially in case of macrocytic associated anemia and chronically elevated CRP among old males, but not exclusively." (PMID 34884286, 2021).